MET (MET proto-oncogene, receptor tyrosine kinase)
Diseases named in the same sentence as MET in open-access papers (continued):
Sharing a sentence is not in itself a finding about the gene and the disease.
tumor (continued). "Taken together, these data were the first to demonstrate H. pylori infection‐induced upregulation of activated MET in exosomes and the pro‐tumorigenic effect on tumour‐associated macrophages." (PMID 30160350, 2018). "High expression of c-MET is associated with tumor invasion and lymph node and hepatic metastasis in CRC." (PMID 30360560, 2018). "Early generations of bivalent anti-MET antibodies have been largely unsuccessful because these antibodies exerted an agonistic effect causing proliferation of both normal cells and tumor cells." (PMID 29725606, 2018). "Elevated matriptase expression is significantly associated with tumor aggressiveness through activated HGF-induced phosphorylation of MET." (PMID 29890660, 2018). "A high sHGF value at later time-points of the treatment course would be associated with activity in the HGF/c-MET signaling pathway in the tumor." (PMID 29069748, 2017). "Accordingly, pharmacological inhibition of MET prevented the tumor-promoting activity of IKKβ-deficient fibroblasts, confirming the significance of HGF/MET signaling for the crosstalk between cancer cells and tumor-promoting fibroblasts." (PMID 28420162, 2017). "Accordingly, activation of the HGF/MET signaling pathway in tumor cells is associated with tumor aggressiveness and resistance to therapy, and predicts poor outcome in cancers patients." (PMID 28420162, 2017). "This outbreak of MET mutations is likely due to reshaping of tumor subpopulations under the selective pressure exerted by crizotinib treatment." (PMID 28460431, 2017). "In 9 patients, the T790M mutation was detected in the tumor re-biopsy displaying MET overexpression or MET amplification." (PMID 29285237, 2017). "Combination of BKM120 and Capmatinib (INC280), a c-Met inhibitor, is investigated in a phase Ib/II clinical trials to assess its safety, dose and anti-tumor activity in patients with recurrent GBM with PTEN loss or MET alteration (NCT01870726)." (PMID 28592260, 2017). "Selectively, in afatinib resistant clones, combined knock down of ERBB3, c-KIT and c-MET caused tumor cell death." (PMID 26934000, 2016). "High expressions of mRNA of HGF and MET in tumor tissues were also associated with poor prognosis in advanced GC patients who underwent gastrectomy." (PMID 26716644, 2016). "This study offers preclinical evidence that MET inhibitors, associated with radiotherapy, not only cause tumor shrinkage, but also reduce the content of GSCs, the source of tumor recurrence." (PMID 27138567, 2016). "Although the CRC cases selected for this study most likely have different mutational spectra, the increased MET gene expression levels in tumor budding foci were consistently observed in every CRC tumor tissue sample analysed." (PMID 27793046, 2016). "Accordingly, constitutive activation of the HGF/MET signaling pathway is associated with tumor aggressiveness, resistance to therapy and predicts poor outcome in many cancers patients." (PMID 27121052, 2016). "Previous reports suggest that c-MET expression is closely associated with both tumor aggressiveness and patient survival." (PMID 26225770, 2015). "The role of c-met in pRCC has not been clearly elucidated but in hereditary pRCC it is suggested that germline mutations of the MET gene promote proliferation, tubulogenesis, and tumour initiation." (PMID 26448938, 2015). "In summary, in the present study the association of high c-MET immunostaining with larger tumours supports involvement of c-MET in tumour progression." (PMID 26459369, 2015). "Current literature empirically suggests that c-MET aberrations (mutations/protein over expression) are more commonly noted in tumor clones with potential to spread." (PMID 26097886, 2015). "High c-MET immunostaining was significantly associated with tumour size larger than 5 cm (p < 0.003) and in left colon subsite (p < 0.05)." (PMID 26459369, 2015).
tumor (continued). "Since many anticancer drugs cause the death of tumor cells through the induction of apoptosis, we thus assume that MET-Har-02 promotes cancer cell apoptosis." (PMID 25940702, 2015). "Based on our in vivo observation that MET-deficient tumors were more differentiated than controls and re-expressed E-cadherin, we examined Slug expression in tumor specimens." (PMID 25888626, 2015). "The current study demonstrates that high protein expression of c-MET protein using immunohistochemical technique was demonstrated to be significantly associated with large tumour size, and left side location of the tumour." (PMID 26459369, 2015). "Overexpression of HGF and c-MET has been shown to exert its effects in tumor progression in association with RhoA and probably with TIMP-3 in pulmonary non-small-cells which promotes EMT and carcinogenesis via up-regulation of COX-2 and Akt." (PMID 28536400, 2015). "MET amplification has been associated with poor prognosis, increased proliferation, tumor invasiveness and angiogenesis." (PMID 26208325, 2015). "Altogether, the data of this manuscript provide further support for the importance of blocking of MET-associated angiogenesis in a hypervascularized microenvironment as that of the liver for efficient tumor growth control." (PMID 26413215, 2015). "In fact, our validation screening revealed frequent mutations in MET, particularly in C2A and C2B tumours." (PMID 25625332, 2015). "On the other hand, high c-MET immunostaining was significantly associated with tumour sizes larger than 5 cm and in left colon location." (PMID 26459369, 2015). "Aberrancy in the HGF/MET pathway has been reported in multiple tumor types and is associated with tumor stage and prognosis." (PMID 28536405, 2015). "In gefitinib or erlotinib resistant tumor samples, about 50% samples have been found to bear T790M mutation and the other 20% cases have c-MET amplification." (PMID 26273639, 2015). "Mutation, amplification, and/or overexpression of the gene encoding MET has been observed in many tumor types, and in many cases has been associated with increased cancer aggressiveness, poor prognosis, and acquired resistance to standard therapies." (PMID 25388653, 2014). "MET expression and function is associated with increased metastasis, tumor aggressiveness and poor prognosis." (PMID 25110867, 2014). "Of note, peripheral edema is a frequently reported toxicity associated anti-HGF/MET antibodies across multiple tumor types and combination regimens." (PMID 24930887, 2014). "Some components of the tumor stroma such as activated cancer-associated pancreatic stellate cells are implicated in neoangiogenesis by activating the c-MET pathway through the release of HGF." (PMID 25483099, 2014). "Metastasis-associated in colon cancer-1 (MACC1) was first identified as a transcriptional activator for proto-oncogene c-MET expression, and its overexpression is frequently associated with metastatic progression for multiply tumor types." (PMID 23497677, 2013). "The c-MET tyrosine kinase receptor has been linked to both tumor angiogenesis and the invasive phenotype of glial and other tumors." (PMID 23484006, 2013). "Amongst others, YB-1 activates gene expression of the epidermal growth factor receptor (EGFR), matrix metalloproteinase 2 (MMP-2) and of the receptor tyrosine kinase c-MET, all this associated with tumor cell adhesion, invasion and metastasis." (PMID 24044901, 2013). "In vivo, NK4 treatments produced the anti-tumor outcomes in mice bearing distinct types of malignant cancers, associated with the loss in MET activation." (PMID 23296269, 2013). "MET oncogene, encodes for the tyrosine kinase receptor for hepatocyte growth factor, has been shown to be over expressed in various type of tumor cells." (PMID 22253909, 2012). "The MET locus is amplified or mutated in selected tumor types, and these patients are predicted to be responsive to treatment with c-Met inhibitors." (PMID 22745804, 2012).
tumor (continued). "The Metproto-oncogene (MET) is the hepatocyte growth factor receptor andhas been implicated in the development of multiple tumor types." (PMID 21359205, 2011). "Activating mutations and MET gene amplification have been found in lung cancer cell lines and primary tumours, resulting in the constitutive activation of the pathway and its cellular effects in cell line models." (PMID 21847116, 2011). "The expression of c-MET and HGF is associated with tumor progression and a number of clinical studies have implicated the prognostic and predictive value of c-MET and/or HGF measurements." (PMID 21283737, 2011). "Key components of the TGF-β and of MET signaling pathways are downmodulated in ULMs, both having a role in cell growth control, tumor progression, and oncogenic effects associated with invasive growth and extracellular matrix remodeling." (PMID 20808773, 2010). "Overexpression of MYC and HGFR/MET is implicated in the aetiology of a variety of tumours and would serve as an important therapeutic target." (PMID 16919171, 2006). "Subcutaneous injection of mutated MET-transfected cells in nude mice leads to the formation of tumours within 12 days in all mice injected." (PMID 15785735, 2005). "The activation of c-MET is frequently associated with high-grade and advanced-stage tumours." (PMID 40078386, 2025). "Importantly, MET overexpression has been implicated in tumor progression and immune evasion, yet its clinical relevance as a predictive biomarker for ICI response remains uncertain." (PMID 41375002, 2025). "Numerous studies have confirmed that c-MET is overexpressed or mutated in various solid tumours, including lung, gastric, liver, breast, skin and colorectal cancers, with significant effects on tumour formation and progression." (PMID 40078386, 2025). "The previous left femur tissue specimen was sent for molecular testing, which showed a PDL-1 (22c3) tumor proportion score of 50%, high tumor mutation burden (11 mutation/megabase), and METex14 skipping mutation, suggesting the benefit of using MET inhibitors, e.g., capmatinib or tepotinib." (PMID 39968425, 2025). "We speculate that loss of MET amplification contributed to resistance and tumor relapse in MET-amplified HCC following crizotinib treatment." (PMID 41268440, 2025). "These mutations were identified in a number of different tumour types suggesting that our findings may have potential implications for treatment of MET‐driven cancers in a histology agnostic manner." (PMID 40437874, 2025). "In addition, while our analysis provides insights into MET mutation and its potential role in NB, further functional studies are required to elucidate its precise contribution to tumor progression and metastasis." (PMID 40386554, 2025). "Since HGF expression by the tumor itself or by its microenvironment may be required for full activation of MET variants having an N‐lobe mutation in HPRCC, HGF expression could be a valuable biomarker in this cancer." (PMID 39980226, 2025). "Moreover, we uncovered significant associations between MET expression and immune cell infiltration within the tumor microenvironment." (PMID 41233563, 2025). "Interestingly, it was recently shown that the HGF/c-MET signaling axis is implicated in tumor proliferation and metastatic spreading of cancer cells." (PMID 40909947, 2025). "Our findings suggest that tumours with specific MET mutations may benefit from MET‐directed therapy that uses a type II agent." (PMID 40437874, 2025). "Moreover, we showed in a model of human HGF knock‐in mice that the pro‐tumour property of ETV1/ERG factors is closely linked to MET activity and proposed a specific molecular signature of this cooperation after conducting a large‐scale transcriptomic analysis." (PMID 39374163, 2025). "Activation of c-MET has also been associated with tumour angiogenesis." (PMID 40078386, 2025).
tumor (continued). "MET amplification causes an abnormal increase in the number of copies of the c-MET proto-oncogene, leading to the uncontrolled growth of cancer cells and tumor formation." (PMID 40656288, 2025). "Even if a tumor lacks MET mutations, it may still respond to treatments that target MET or its downstream pathways." (PMID 38675409, 2024). "However, co-mutations and inhibition of key immune signaling genes by MET alterations that impact tumor immunogenicity must be considered as they can impact response to ICIs." (PMID 39664186, 2024). "Notably, both responders to the combination therapy had previously progressed on erlotinib alone exhibited MET protein tumor expression and had EGFRex19 deletion mutation." (PMID 39449330, 2024). "Our findings revealed that high MET/ESR1 coexpression was associated with favorable clinicopathologic tumor features such as greater age at diagnosis, lower NPI scores, low-grade carcinoma, hormone receptor positivity, HER2-negative status, and luminal subtype." (PMID 39742369, 2024). "This suggests that MET can serve as a therapeutic target for TKI treatment while high MET expression may also be a cause of tumor TKI targeting resistance." (PMID 39605750, 2024). "Additionally, c-MET has been identified as a significantly expressed tumor-associated antigen across various tumor types." (PMID 39664377, 2024). "This discrepancy could partially result from the fact that pHGG, especially IHG, typically lacks large-scale structural, copy number, or single nucleotide variants, rendering the tumor exclusively dependent on the oncogenic RTK such as MET." (PMID 38849845, 2024). "Furthermore, REGN5093-M114 effectively reduced tumor growth in EGFR-mutant NSCLC cases with PTEN loss or c-MET-Y1230C mutation, even in cases of prior progression on osimertinib and savolitinib treatment." (PMID 39664377, 2024). "However, for patients who require adjustment of treatment after targeted therapy, a tumor cellularity of ≥ 20% is needed to determine the presence of acquired resistance mutations, such as T790M and MET amplification." (PMID 38902688, 2024). "In addition, Hp can induce upregulation of MET in GC cell exosomes and enhance the pro tumor effect of tumor associated macrophages." (PMID 38463229, 2024). "Additionally, it correlates with the overexpression of tumor-promoting factors such as VEGF and MET, and with more aggressive tumor variants like the tall cell variant of PTC." (PMID 39363900, 2024). "Detection of these mutations in tumours suggests that they may play a direct role in resistance through ligand-independent MET activation." (PMID 38652103, 2024). "We identified a circRNA encoded by the MET gene (circMET) and exploited blood-derived cell-free RNA (cfRNA) and matched tumor tissues to identify, stratify and monitor advanced cancer patients molecularly characterized by high MET activity, generally associated with genomic amplification." (PMID 37170152, 2023). "The c-mesenchymal-epithelial transition protooncogene (MET) is an important gene that encodes the MET protein, which functions as a transmembrane receptor tyrosine kinase and may trigger tumor growth under aberrant activation." (PMID 36969059, 2023). "Therefore, to potentially complement sNGS, we validated the Idylla Genefusion assay for ALK, ROS1, and RET rearrangements and MET exon 14 skipping variant detection using 34 tumor samples that were previously orthogonally tested via FISH and NGS." (PMID 37628603, 2023). "Moreover, patients showing modifications of CEBPA, FGFR4, MET or KMT2B genes detected in circulating tumor DNA before ICI initiation are at higher risk of experiencing irAEs." (PMID 36900420, 2023).
tumor (continued). "Indeed, upregulation in plasma and plasma HGF, soluble MET, and phosphor-MET have been associated with primary and distant tumor progression, resistance to therapy, and overall poorer outcomes." (PMID 38067195, 2023). "While it is unclear whether HGF activates MET in a paracrine or autocrine way, elevated tumor-stroma interactions were associated with unfavorable responses to EGFR TKI in clinical practice." (PMID 36647832, 2023). "The mutation of MET plays a crucial role in the initiation of cancer, while the Hedgehog (Hh) pathway also plays a significant role in cell differentiation and the maintenance of tumor stem cells." (PMID 37919751, 2023). "Beyond the well-known ERBB2/HER2 or MET amplification-associated dependencies, there are other gene dependencies identified in the analysis that show promising results in selected tumor types." (PMID 36980521, 2023). "Tumor development is also associated with the amplification of the tyrosine kinase receptor c-MET along with its ligand HGF (hepatocytes growth factor), as numerous biological processes, including reproduction, viability, mobility, and penetration, are controlled by c-MET." (PMID 37102943, 2023). "Overexpression of MET may be the primal causative event in tumor invasion and metastasis induced by VHL loss suggesting its utility as a potential downstream candidate in the context of HIF-α overexpression." (PMID 36831657, 2023). "We then evaluated associations between MACC1 or MET expressions and tumor progression." (PMID 37496665, 2023). "In addition, in the high-risk RMS tumor cells used in the present work MET is basally overexpressed and activated and NOTCHi further increases its activation thus possibly making it a major target of ARQ inhibition." (PMID 35574376, 2022). "Already, clinical trials testing the efficacy of MET inhibitors in METΔexon14-presenting tumours have identified amplification and/or activating mutations in the KRAS or BRAF genes (as well as activating mutations in the PI3K-AKT pathway) to be a common form of acquired resistance." (PMID 35326531, 2022). "Furthermore, circ-PDE8A facilitated tumor cell growth by increasing the expression of MET (a tyrosine kinase receptor), encoded by one of the vital oncogenes for a subclass of epithelial tumors, containing PDA." (PMID 34987636, 2022). "In conclusion, in bevacizumab-treated patients diagnosed with EOC, high c-MET/VEGFR-2 co-localisation on tumour tissue and the VEGFR-2 rs2305945 G/G variant, which may be biologically related, was associated with worse survival outcomes." (PMID 35144591, 2022). "Furthermore, constitutive activation of the HGF/c-MET signaling pathway in cancer patients is linked to tumor aggressiveness, drug resistance, and poor prognosis." (PMID 35630066, 2022). "In our study, the KRAS G12C mutation was associated with a MET mutation in four cases, indicating that there might be a need for adaptive treatment regimens according to the specific mutational profile of the tumor." (PMID 35205778, 2022). "Interestingly, we found that the mRNA expression levels of DPP4/CTNNB1/MET are inversely associated with tumor purity." (PMID 35205190, 2022). "Subsequent identification of ALK rearrangements and several cancer‐driver events, including ROS1, NRG1, NTRK1/RET fusion, BRAF (V600E) mutation, or MET amplification/Exon14 skipping, strengthened the concept of oncogene addiction and tumor heterogeneity as a pillar of modern cancer therapeutics." (PMID 35838331, 2022). "The MET oncogene encodes for a receptor tyrosine kinase with pleiotropic functions in initiating and sustaining neoplastic transformation, as well as in cancer cell survival and tumour dissemination." (PMID 35552415, 2022). "In bevacizumab-treated women diagnosed with EOC, high c-MET/VEGFR-2 co-localisation on tumour tissue and the VEGFR-2 rs2305945 G/G variant, which may be biologically related, were associated with worse survival outcomes." (PMID 35144591, 2022).